CT47A2 (cancer/testis antigen family 47 member A2)
Synonyms: CT47.2
Gene: Protein-coding gene on chromosome X (120,977,606 to 120,980,928, reverse strand). Ensembl gene ENSG00000242362.
Subcellular location (Human Protein Atlas): Nucleoli
Homologues: Orthologues: macaque CT47B1 (77% identical). Paralogues in human: CT47A1 (100% identical), CT47A10 (100% identical), CT47A11 (100% identical), CT47A12 (100% identical), CT47A3 (100% identical), CT47A4 (100% identical), CT47A5 (100% identical), CT47A6 (100% identical), CT47A7 (100% identical), CT47A8 (100% identical), CT47A9 (100% identical), CT47B1 (86% identical), and 1 more.